TRAM2 (translocation associated membrane protein 2)
Description:
Necessary for collagen type I synthesis. May couple the activity of the ER Ca(2+) pump SERCA2B with the activity of the translocon. This coupling may increase the local Ca(2+) concentration at the site of collagen synthesis, and a high Ca(2+) concentration may be necessary for the function of molecular chaperones involved in collagen folding. Required for proper insertion of the first transmembrane helix N-terminus of TM4SF20 into the ER lumen, may act as a ceramide sensor for regulated alternative translocation (RAT).
Synonyms: KIAA0057
Tractability: Antibody: UniProt predicts a signal peptide or a membrane-spanning region. PROTAC: ubiquitination databases record sites on it; its protein half-life has been measured.
Gene: Protein-coding gene on chromosome 6 (52,497,408 to 52,577,077, reverse strand). Ensembl gene ENSG00000065308.
Subcellular location: Membrane
Subcellular location (Human Protein Atlas): Cytosol
Gene Ontology:
Molecular function: protein binding
Biological process: collagen biosynthetic process; protein insertion into ER membrane; SRP-dependent cotranslational protein targeting to membrane, translocation
Cellular component: endoplasmic reticulum membrane; membrane
Genetic constraint (gnomAD): Loss-of-function variants: 11 observed, 52.18 expected, observed/expected ratio (o/e) 0.21, 90% interval 0.13 to 0.35. The upper end of that interval is the gene's LOEUF score, 0.35, which puts it in group 1 of 6, group 1 being the genes least tolerant of losing a copy. Missense variants: 357 observed, 477.44 expected, observed/expected ratio (o/e) 0.75, 90% interval 0.69 to 0.82. Synonymous variants: 175 observed, 190.97 expected, observed/expected ratio (o/e) 0.92, 90% interval 0.81 to 1.04.
Homologues: Orthologues: chimpanzee TRAM2 (99% identical), macaque TRAM2 (99% identical), dog TRAM2 (97% identical), guinea pig TRAM2 (95% identical), mouse Tram2 (90% identical), rat Tram2 (90% identical), pig TRAM2 (85% identical), rabbit TRAM2 (84% identical), tropical clawed frog tram2 (75% identical), zebrafish tram2 (66% identical), Drosophila melanogaster TRAM (38% identical), Caenorhabditis elegans tram-1 (35% identical). Paralogues in human: TRAM1 (52% identical), TRAM1L1 (45% identical).
Diseases named in the same sentence as TRAM2 in open-access papers:
TRAM2 is named in the same sentence as 11 diseases in open-access papers, as found by Europe PMC text mining. Sharing a sentence is not in itself a finding about the gene and the disease. The quoted sentences say what the papers report.
breast carcinoma (2 papers, 2022 to 2025). "TRAM2 is driven by an enhancer to induce epithelial-to-mesenchymal cell transition in breast cancer cells, which is involved in cell proliferation invasion and migration, and high TRAM2 expression is associated with poor survival in cancer patients." (PMID 40427520, 2025). "Additionally, the transcript of TRAM2-TCNE was significantly overexpressed in breast cancer cell lines and was able to potentially perform the eRNA function, promoting the formation of enhancer-promoter looping." (PMID 40427520, 2025). "Meanwhile, TRAM2-TCNE was detected to be significantly overexpressed in three breast cancer cell lines, MCF-7, T-47D, and BT-474, compared to a non-tumorigenic mammary epithelial cell line, MCF-12A." (PMID 40427520, 2025). "Studies have shown that TRAM2 promotes the proliferation and invasion of oral and breast cancer cells, but no reports have demonstrated the role of TRAM2 in HCC cells." (PMID 35494016, 2022).
glioma (2 papers, 2022). A benign or malignant brain and spinal cord tumor that arises from glial cells (astrocytes, oligodendrocytes, ependymal cells). "The researchers further demonstrated that silencing of TRAM2 blocked the malignant progression of glioma by inhibiting the PI3K/Akt/mTOR signaling, rendering it a pathway with therapeutic potential." (PMID 36425564, 2022). "A recent study found that TRAM2 is over-expressed in glioma samples and cell lines, and that higher expression was associated with poor survival." (PMID 36425564, 2022). "In glioma, through its PI3K/AKT/mTOR signaling pathway regulation, TRAM2 is able to enhance tumor cells migration, invasion, proliferation, and EMT." (PMID 36618348, 2022).
hepatocellular carcinoma (2 papers, 2022 to 2025). A malignant tumor that arises from hepatocytes. "According to the report, RBM15B enhanced TRAM2 mRNA stability by relying on its m6A methyltransferase activity in the TRAM2 3'‐UTR, thereby promoting hepatocellular carcinoma proliferation." (PMID 40066751, 2025).
COVID-19 (1 paper, 2024). A disease caused by infection with severe acute respiratory syndrome coronavirus 2. "The Gpnmb RecAM gene signature had significant enrichment in monocyte-derived macrophages (MoAM3) and SARS-CoV-2–infected RAM (TRAM2) in BAL from patients with severe COVID-19." (PMID 39509324, 2024).
liver cancer (1 paper, 2022). An epithelial or non-epithelial malignant neoplasm that arises from the liver. "TRAM2 can activate YAP to promote tumor growth and metastasis, but no research has been conducted to clarify the function of TRAM2 in liver cancer." (PMID 35494016, 2022).
oral squamous cell carcinoma (1 paper, 2019). "Interestingly, TRAM2 (for translocation associated membrane protein 2), a component of the SEC61 translocation channel located at ER, is highly expressed in oral squamous cell carcinoma and has a main role in metastasis by controlling PERK activation and the expression of MT1-MMP, MMP2, and MMP9." (PMID 31064137, 2019).
osteosarcoma (1 paper, 2022). A usually aggressive malignant bone-forming mesenchymal neoplasm, predominantly affecting adolescents and young adults. "Our study first revealed that TRAM2 expression in osteosarcoma cell lines was higher than the human osteoblast cell line according to Western blot results." (PMID 36618348, 2022). "Then, si-TRAM2 was transferred to HOS and U2OS cell lines to discover the effect of TRAM2 on the osteosarcoma cell progression." (PMID 36618348, 2022). "TRAM2 protein expression was demonstrated to be significantly different across the osteosarcoma and the human osteoblast cell lines during experimental validation." (PMID 36618348, 2022). "In cytological experiments, we selected TRAM2 as a representative gene to validate the validity of GCSRGs signature, which found that TRAM2 promoted the progression of osteosarcoma cells." (PMID 36618348, 2022). "Therefore, TRAM2 is expected to emerge as a promising new biological target in osteosarcoma treatment." (PMID 36618348, 2022). "Although we confirmed the effective role of the GCSRGs signature in predicting the prognosis of osteosarcoma patients and confirmed the tumor-promoting effect of TRAM2 in osteosarcoma cells in cytological experiments in vitro, this study still has certain drawbacks that require further research." (PMID 36618348, 2022). "In addition, inhibiting of EMT-related protein expression, cell viability, colony formation, migration, and invasion were achieved by downregulating TRAM2 protein expression in osteosarcoma cells." (PMID 36618348, 2022). "However, studies on the mechanism of TRAM2 action in osteosarcoma are scarce." (PMID 36618348, 2022). "Both univariate and LASSO Cox regression analyses were conducted on screened module genes to identify 5 GCSRGs (RPS28, MCAM, EN1, TRAM2, and VEGFA) constituting a prognostic signature for osteosarcoma patients." (PMID 36618348, 2022). "However, no relevant studies have shown the relationship between TRAM2 and osteosarcoma." (PMID 36618348, 2022).
cancer (6 papers, 2021 to 2025). A tumor composed of atypical neoplastic, often pleomorphic cells that invade other tissues. "EMT is associated with cancer resistance and aggressive behavior, and the fact that TRAM2 plays a causal role in these phenotypes indicates that TRAM2 is a key determinant in YAP signaling." (PMID 33514403, 2021). "Notable examples—such as ANO1, BAG2, DHCR7, MMP2, and TRAM2 —align with prior studies linking these genes related to cancer proliferation or metastasis in multiple cancer types." (PMID 40361356, 2025). "To further analyze the important role of TRAM2 in other malignant tumors, we performed pan-cancer analysis of TRAM2." (PMID 36618348, 2022). "TRAM2 is a crucial determinant of cancer biology, including cell proliferation and chemotherapeutic drug resistance, and has a significant impact on prognosis." (PMID 35494016, 2022). "Gene expression datasets of many different cancer types confirmed this conclusion by pinpointing a strong link between TRAM2 and YAP gene expression signature, and a strong association with poor cancer patient survival." (PMID 33514403, 2021). "In light of the key role of TRAM2 in YAP-mediated migration and invasion phenotypes, we investigated the association of its expression with cancer patient survival from the TCGA database." (PMID 33514403, 2021). "Therefore, to ensure the validity of the GCSRGs signature, we chose to use TRAM2 for cell function validation and pan-cancer analysis." (PMID 36618348, 2022). "Finally, at the pan-cancer level, TRAM2 had been correlated with overall survival, progression free survival, disease specific survival, tumor mutational burden, microsatellite instability, immune checkpoints and immune cells infiltration." (PMID 36618348, 2022). "In addition, TRAM2 and YAP activity in various cancers shows a very strong expression correlation, demonstrating that TRAM2 acts a significant role in malignant proliferation and invasion caused by YAP." (PMID 36618348, 2022). "Thus, while our observations tightly tied TRAM2 to YAP signaling network in cancer, and demonstrated TRAM2’s link to cancer patients’ survival rates, they also indicated that other important targets of YAP are required to sustain tumorigenic expansion in vivo." (PMID 33514403, 2021). "Beyond the known targets of YAP (i.e., MYC and CCND1), we uncovered TRAM2 (translocation chain-associated membrane 2) and described its contribution to cellular proliferation, epithelial to mesenchymal transition (EMT), and cellular migration and invasion, as well as cancer prognosis." (PMID 33514403, 2021). "The genetic link between TRAM2 and YAP, their co-expression in cancer datasets, and the induction of similar phenotypes (EMT, migration and invasion) prompted us to examine the effect of TRAM2 on in vivo tumor growth." (PMID 33514403, 2021). "Moreover, it has been reported that collagen contributes to cancer progression, such as invasion, metastasis which is also in line with the EMT induced by TRAM2." (PMID 33514403, 2021). "We focused on TRAM2 in this manuscript because of its unknown link with YAP and cancer progression." (PMID 33514403, 2021). "However, TRAM2 was never linked to YAP, cellular proliferation, and human cancer." (PMID 33514403, 2021). "Furthermore, while a functional genetic interaction between YAP and TRAM2, KIF18A, TMEM158, and SLC39A1 was never reported, the role of TMEM158, KIF18A, and SLC39A1 in cell proliferation or cancer progression was already established before." (PMID 33514403, 2021).
tumor (5 papers, 2021 to 2025). "Overexpression of TRAM2 attenuated the reduction in subcutaneous tumor volume in nude mice caused by knockdown of RBM15B." (PMID 35494016, 2022). "We focus on EnhancerTRAM2, as its target gene TRAM2 shows the strongest expression-correlation with YAP activity in nearly all tumor types." (PMID 33514403, 2021). "This identified a positive correlation between tumor TRAM2-expression and poor survival probability of patients in 8 TCGA studies." (PMID 33514403, 2021). "Altogether, these data support a key role of TRAM2 as a mediator of YAP-induced tumor aggressiveness and poor patient survival probability." (PMID 33514403, 2021). "A full-blown tumor growth requires the activation by YAP of other targets than TRAM2." (PMID 33514403, 2021). "In contrast, TRAM2 was only sufficient to initiate tumor growth but not to sustain its expansion." (PMID 33514403, 2021).
infection (2 papers, 2019). The state of being infected such as from the introduction of a foreign agent such as serum, vaccine, antigenic substance or organism. "On the other hand, neither TRAM2 depletion nor Thapsigargin treatment had any effects on type I collagen production during host cell infection, pointing towards an alternative role of TRAM2 on S. aureus intracellular survival in this context." (PMID 31659191, 2019). "This change in the migration pattern was proportional to the MOI employed for the infection, suggesting that S. aureus may be interfering with the post-translational modification of TRAM2 to promote its own survival or replication." (PMID 31659191, 2019). "In contrast, treatment of infected HeLa cells with low doses of Thapsigargin resulted in a significantly attenuated bacterial load at both time points of infection (at 2 and 6 hours post infection), whereas this reduction was only observed after 6 hours of infection in TRAM2 knockdown cells." (PMID 31659191, 2019). "We found that silencing the human gene TRAM2 resulted in a significant reduction of intracellular bacterial load while host cell viability was restored, showing its importance during intracellular infection." (PMID 31659191, 2019). "To shed light on the role of TRAM2 on S. aureus intracellular survival, we have first evaluated the effect of S. aureus infection on the protein levels of TRAM2 in wild type HeLa cells at different time points and multiplicity of infections (MOI)." (PMID 31659191, 2019). "Based on this evidence, we hypothesized that by silencing TRAM2 in HeLa cells we may in turn block Ca2+ pumps of the ER (e.g. SERCA2b), and consequently alter the maturation of proteins that are essential for S. aureus during cell infection." (PMID 31659191, 2019). "In particular, we found that silencing the human gene TRAM2 resulted in a significant reduction of intracellular MRSA, whereas host cell viability was restored, showing its importance during intracellular infection." (PMID 31795127, 2019). "However, at 6 hours post-infection, we noticed a change in the migration pattern of TRAM2 upon denaturing protein electrophoresis that apparently generates a band of lower molecular weight, indicating that TRAM2 may have been subjected to post-translational modification such as proteolysis." (PMID 31659191, 2019). "Moreover, TRAM2 silencing did not have an effect during early time points of infection (i.e. 2 hours post-infection), pointing towards a role on intracellular proliferation rather than cell entry." (PMID 31659191, 2019). "We selected CD83, FAM63B, MYL2 and TRAM2 knockdowns for further analysis since the silencing of these four host genes resulted in increased host cell viability regardless of the strain that was employed, and these genes were not studied before in relation to S. aureus cell infection." (PMID 31659191, 2019). "Taken together the low number of co-localization events, we can only conclude that either TRAM2 co-localization is highly dynamic or this protein may have other roles during cell infection rather than on the maturation of the vacuole containing intracellular S. aureus." (PMID 31659191, 2019).
TRAM2 also shares sentences with these, for which no sentence is quoted: Obesity (1 paper).